TXNL1 (thioredoxin like 1)
Description:
Active thioredoxin with a redox potential of about -250 mV.
Synonyms: TRP32; TXL; TXNL; HEL-S-114; TXL-1
Tractability: Small molecule: a structure with a bound ligand is known. PROTAC: ubiquitination databases record sites on it; its protein half-life has been measured.
Target class: Enzyme; Oxidoreductase
Gene: Protein-coding gene on chromosome 18 (56,597,209 to 56,651,600, reverse strand). Ensembl gene ENSG00000091164.
Subcellular location: Cytoplasm; Nucleus
Subcellular location (Human Protein Atlas): Cytosol
Pathways (Reactome):
Signal Transduction: RHOBTB1 GTPase cycle; RHOBTB2 GTPase cycle; RHOU GTPase cycle; RHOV GTPase cycle; RND1 GTPase cycle; RND2 GTPase cycle; RND3 GTPase cycle
Gene Ontology:
Molecular function: disulfide oxidoreductase activity; protein-disulfide reductase activity
Cellular component: cytoplasm; cytosol; nucleus
Genetic constraint (gnomAD): Loss-of-function variants: 13 observed, 30.55 expected, observed/expected ratio (o/e) 0.43, 90% interval 0.28 to 0.68. The upper end of that interval is the gene's LOEUF score, 0.68, which puts it in group 2 of 6, group 1 being the genes least tolerant of losing a copy. Missense variants: 235 observed, 324.6 expected, observed/expected ratio (o/e) 0.72, 90% interval 0.65 to 0.81. Synonymous variants: 99 observed, 109.83 expected, observed/expected ratio (o/e) 0.9, 90% interval 0.76 to 1.07.
Homologues: Orthologues: mouse Txnl1 (99% identical), pig TXNL1 (97% identical), chimpanzee TXNL1 (97% identical), dog TXNL1 (97% identical), rabbit TXNL1 (97% identical), guinea pig TXNL1 (97% identical), macaque TXNL1 (97% identical), rat Txnl1 (96% identical), tropical clawed frog txnl1 (84% identical), zebrafish txnl1 (81% identical), Drosophila melanogaster Txl (49% identical), Caenorhabditis elegans txl-1 (45% identical). Paralogues in human: TXN (17% identical), TXNDC2 (15% identical), TXNDC8 (15% identical), TXN2 (12% identical).
Diseases named in the same sentence as TXNL1 in open-access papers:
TXNL1 is named in the same sentence as 16 diseases in open-access papers, as found by Europe PMC text mining. Sharing a sentence is not in itself a finding about the gene and the disease. The quoted sentences say what the papers report.
breast carcinoma (1 paper, 2022). "Our results found TXNL1 as a novel 5-hmC candidate gene in breast cancer with an increased 5-hmC level and corresponding gene overexpression." (PMID 36230901, 2022). "Our validation analysis confirmed that the gain of 5-hmC in TXNL1, BNIPL, CNIH3 and loss of 5-hmC in CHODL, ZBTB16, SP8, and HIC2 in breast cancer samples." (PMID 36230901, 2022). "Novel 5-hmC candidates such as TXNL1, CNIH3, BNIPL, and CHODL were found to be promising diagnostic and therapeutic markers for breast cancer." (PMID 36230901, 2022). "Survival analysis also indicated the overexpression of TXNL1 and BNIPL in breast cancer is significantly associated with poor overall survival." (PMID 36230901, 2022). "Further functional analysis on the 5-hmC gain at TXNL1 and other loci would be warranted to elucidate the mechanistic insight of 5-hmC in the transcriptional activation and breast cancer development." (PMID 36230901, 2022). "The novel 5-hmC candidates such as TXNL1, and CNIH3 implicate a pro-oncogenic role in breast cancer." (PMID 36230901, 2022).
epilepsy (1 paper, 2025). A brain disorder characterized by episodes of abnormally increased neuronal discharge resulting in transient episodes of sensory or motor neurological dysfunction, or psychic dysfunction. "In a PTZ seizure mouse model for evaluation of epilepsy, the protein expression levels of thioredoxin-1 (TRX1), thioredoxin-like 1 protein (TXNL1), and thioredoxin reductase 1 (TXNRD1) were upregulated in the cortex of both acute and chronic groups." (PMID 40943128, 2025).
fungal infection (1 paper, 2017). "Interestingly, low expression (less than two-fold) of DUOX1, PRXS1L and TXNL1 was observed upon fungal infection among winged imagoes, nymphs, soldiers and workers." (PMID 29231889, 2017).
gastric cancer (1 paper, 2018). A primary or metastatic malignant neoplasm involving the stomach. "Furthermore, TXNL1 can resist cisplatin by interacting with X-ray repair cross complementing group 1 (XRCC1) in human gastric cancer." (PMID 30290847, 2018). "TXNL1 has been reported to induce apoptosis by downregulating Bcl-2 in gastric cancer cells." (PMID 30290847, 2018). "TXNL1 has been reported to induce apoptosis in cisplatin-resistant human gastric cancer cell lines." (PMID 30290847, 2018).
non-spherocytic hemolytic anemia (1 paper, 2025). "A study reported that in two patients with hereditary non-spherocytic hemolytic anemia, the expression levels of thioredoxin-like 1 protein were elevated compared to controls." (PMID 40943128, 2025).
cancer (3 papers, 2022 to 2025). A tumor composed of atypical neoplastic, often pleomorphic cells that invade other tissues. "Notably, auranofin treatment did not provoke the strong downregulation of TXNL1 typically seen previously in proteomics studies using cancer cell line models, and neither auranofin nor TRi-1 seemed to have triggered clear upregulation of NRF2 targets in this data set." (PMID 41300507, 2025).
tumor (2 papers, 2020). "We found two deleted regions shared by both tumor types in three out of the four cell lines H23R, A2780R, and OVCAR3R, but not in H460 cells, located on 18q21.2–18q21.31 and 18q21.32, affecting the genes RAB27B, CCDC68, TCF4, TXNL1, WDR7, and BOD1P; and genes ZNF532, SEC11C, GRP, respectively." (PMID 32224864, 2020).
TXNL1 also shares sentences with these, for which no sentence is quoted: infection (7 papers); acute coronary syndrome (1); alopecia (1); cardiomyopathy (1); diabetes (1); dilated cardiomyopathy (1); heart failure (1); Insulin resistance (1); scoliosis (1).